CCL2 (C-C motif chemokine ligand 2)
Description:
Acts as a ligand for C-C chemokine receptor CCR2. Signals through binding and activation of CCR2 and induces a strong chemotactic response and mobilization of intracellular calcium ions. Exhibits a chemotactic activity for monocytes and basophils but not neutrophils or eosinophils. May be involved in the recruitment of monocytes into the arterial wall during the disease process of atherosclerosis.
Synonyms: MCAF; MCP-1; MCP1; SCYA2; SMC-CF; GDCF-2; HC11; MGC9434; HSMCR30
Tractability: Small molecule: a high-quality ligand is known. Antibody: a drug acting on it is in phase 2 or 3 trials; UniProt places it where antibodies can reach, with high confidence; its Gene Ontology location is reachable by antibodies, with high confidence; UniProt predicts a signal peptide or a membrane-spanning region. PROTAC: a small molecule that binds it is known.
Target class: Secreted protein
Gene: Protein-coding gene on chromosome 17 (34,255,274 to 34,257,208, forward strand). Ensembl gene ENSG00000108691.
Subcellular location: Secreted
Subcellular location (Human Protein Atlas): Golgi apparatus; Vesicles; Predicted to be secreted
Pathways (Reactome):
Cellular responses to stimuli: ATF4 activates genes in response to endoplasmic reticulum stress; NFE2L2 regulating inflammation associated genes
Immune System: Interleukin-10 signaling; Interleukin-4 and Interleukin-13 signaling
Signal Transduction: Chemokine receptors bind chemokines
Gene Ontology:
Molecular function: chemoattractant activity; chemokine activity; chemokine receptor binding; protein binding; CCR chemokine receptor binding; CCR2 chemokine receptor binding; protein kinase activity; signaling receptor binding
Biological process: astrocyte cell migration; cellular response to fibroblast growth factor stimulus; cellular response to interleukin-1; cellular response to tumor necrosis factor; cellular response to type II interferon; chemokine-mediated signaling pathway; cytokine-mediated signaling pathway; cytoskeleton organization; macrophage chemotaxis; monocyte chemotaxis; negative regulation of G1/S transition of mitotic cell cycle; negative regulation of glial cell apoptotic process; negative regulation of natural killer cell chemotaxis; negative regulation of neuron apoptotic process; negative regulation of vascular endothelial cell proliferation; positive regulation of calcium ion import; positive regulation of cytosolic calcium ion concentration; positive regulation of endothelial cell apoptotic process; regulation of cell shape; angiogenesis; animal organ morphogenesis; antimicrobial humoral immune response mediated by antimicrobial peptide; cell adhesion; cell surface receptor signaling pathway; cell surface receptor signaling pathway via JAK-STAT; and 24 more
Cellular component: extracellular region; membrane
Genetic constraint (gnomAD): Loss-of-function variants: 2 observed, 2.34 expected, observed/expected ratio (o/e) 0.86, 90% interval 0.33 to 1.84. That is too few expected variants to judge how well the gene tolerates losing a copy. Missense variants: 74 observed, 98.24 expected, observed/expected ratio (o/e) 0.75, 90% interval 0.62 to 0.91. Synonymous variants: 33 observed, 38.36 expected, observed/expected ratio (o/e) 0.86, 90% interval 0.65 to 1.15.
Homologues: Orthologues: macaque CCL2 (97% identical), chimpanzee CCL2 (82% identical), dog CCL2 (80% identical), pig CCL2 (80% identical), rabbit CCL2 (73% identical), guinea pig Ccl2 (57% identical), mouse Ccl2 (53% identical), rat Ccl2 (52% identical), zebrafish cxcl32b.1 (32% identical). Paralogues in human: CCL7 (74% identical), CCL11 (70% identical), CCL8 (69% identical), CCL13 (65% identical), CX3CL1 (37% identical), CCL23 (35% identical), CCL21 (34% identical), CCL3L3 (34% identical), CCL3 (32% identical), CCL4 (32% identical), CCL15 (31% identical), CCL16 (31% identical), and 14 more.
Diseases named in the same sentence as CCL2 in open-access papers:
CCL2 is named in the same sentence as 1,196 diseases in open-access papers, as found by Europe PMC text mining. Sharing a sentence is not in itself a finding about the gene and the disease. The quoted sentences say what the papers report.
Obesity (1,014 papers, 2007 to 2026). Accumulation of substantial excess body fat. "This cancer–adipose crosstalk, validated in 3D coculture, obese mouse models, and breast cancer tissues, underscores CCL2 blockade as a potential therapy for obesity‐associated cancers." (PMID 41160815, 2026). "In conditions of HNRNPA1 deficiency, as observed in obesity, the regulatory mechanism is disrupted, resulting in a significant enhancement of CCL2 protein synthesis and secretion by adipocytes." (PMID 41596407, 2026). "GATA3 upregulation in the VAT of subjects with obesity increased IL-6 secretion, which in turn activated macrophage infiltration by upregulating monocyte chemoattractant protein-1 (MCP-1, encoded by the CCL2 gene)." (PMID 40423250, 2025). "A hallmark of obesity is chronic low-grade inflammation, primarily initiated by dysfunctional adipocytes secreting chemokines such as CCL2, which drive the infiltration of immune cells—most notably macrophages." (PMID 41310829, 2025). "The secretion of CCL2 by adipocytes, along with other adipokines, appears to be more closely associated with obesity‐related risks than other adipokines." (PMID 40518865, 2025). "Chemokines, such as the monocyte chemoattractant protein 1 (MCP‐1, encoded by Ccl2), play crucial roles in recruiting circulating monocytes (Lgals3, Galectin 3+) into AT in the presence of obesity." (PMID 40847538, 2025). "Previous studies have shown that visceral adipose tissue secretes CCL2 in obesity, and that CCL2 levels decrease with weight loss." (PMID 40731922, 2025). "Obesity-associated signals such as CCL2, CSF1, and leptin not only increase macrophages infiltration but also direct their spatial recruitment to metabolically stressed or angiogenic regions of the tumor." (PMID 41310829, 2025). "In summary, these data provide further evidence that CKB and CCL2 dysregulation in obesity is linked to increased CpG methylation of the proximal promoter region of CKB." (PMID 39675471, 2024). "MCP-1, also known as CCL2, is a biomarker linked to metabolic disorders like type 2 diabetes and obesity." (PMID 38255264, 2024). "similarly, exercise reduces CCL2 secretion that also reduces the inflammatory response associated with obesity." (PMID 39334887, 2024). "An upregulation of TLR4 (P < 0.05), CD68 (P < 0.05), SPP1 (P < 0.05) and CCL2 (P < 0.05) together with a downregulation (P < 0.05) of ADIPOQ levels in the jejunum from patients with obesity-associated T2D were found." (PMID 38315242, 2024). "High expression of CCL2 in obese tissues, which is closely associated with obesity-induced cardiovascular disease and insulin resistance, promotes the migration of monocytes to adipose tissue." (PMID 39334887, 2024). "The pathway of elevated CCL2 gene expression associated with obesity specifically involves Interferon-gamma (IFN-γ) pretreatment." (PMID 39334887, 2024). "Increased histone acetylation in the tumor necrosis factor (Tnfa) and monocyte chemotactic protein 1 (Mcp1/Ccl2) inflammatory cytokine genes has also been associated with fatty liver disease in mouse models of obesity." (PMID 38790268, 2024). "Recent studies have shown that higher CCL2 concentrations are associated with the risks of early IR and the development of obesity." (PMID 36675322, 2023). "Obesity-associated increased production of serum amyloid A is accompanied by the overproduction of hyaluronan that, together with monocyte chemoattractant CCL2, exhibit similar functions." (PMID 37432145, 2023). "Obesity-associated pro-inflammatory molecules (e.g., TNFα, FFAs, Resistin, AGEs, and CCL-2) can cross the BBB, propelling hypothalamic inflammation." (PMID 36829858, 2023). "Obesity, another risk factor for pancreatic cancer, can induce inflammation by promoting the release of IL-6, CCL2, and CCL5, and the infiltration of macrophages and immunosuppressive cells." (PMID 36899319, 2023).
Obesity (continued). "To investigate the colonic macrophage infiltration underlying dietary obesity, we evaluated the changes of CCL2 and F4/80 under HFD and LAB treatment." (PMID 36911680, 2023). "Pre-gravid obesity is associated with elevated levels of C-C Motif Chemokine Ligand 2 (CCL2) and CXCL8, which are recruiting factors in the blood during pregnancy." (PMID 37515062, 2023). "Adipose tissue expression of CCL2 is increased in obesity, and we have shown that loss of CCR2 signaling reduces fibrocytes within the obese mammary gland." (PMID 38041006, 2023). "Recent research has shown that higher concentrations of CCL2 in serum correlated with early IR, carbohydrate metabolism disorder, obesity development, and preeclampsia development risk." (PMID 35211112, 2022). "This is possibly linked via the chemokine CCL2, which is increased in obesity and important in monocyte mobilization and correlated to the number of monocytes in circulation." (PMID 36466916, 2022). "CCL2 is known to be associated with obesity, diabetes, cardiovascular disease, insensitivity, diabetic nephropathy, diabetic retinopathy, and other diseases." (PMID 36289628, 2022). "Obesity is associated with an increase in adipose tissue size and results in the activation of macrophage inflammatory factors including TNFα, IL-6, and MCP-1 (CCL2), which causes insulin resistance." (PMID 34299302, 2021). "Growing evidence has revealed that obesity is associated with immune response involving chemokines secreted by immune cells, such as CCL2, and CCL5." (PMID 34948325, 2021). "Abrogation of the signal pathways of CXCL14, CXCL5, CCL2, or their cognate chemokine receptors, alleviated obesity-associated metabolic abnormalities in high fat diet (HFD)-induced obese mice." (PMID 34948325, 2021). "At T1, obesity was associated with a 2-fold increase of myeloid cell chemoattractants CCL2 and 1.5-fold increase in circulating CCL4." (PMID 34195568, 2021). "The obesity skewed immune responsiveness, which broadly favors proinflammatory cytokine (e.g., IL-6, TNF) and chemokine (e.g., CCL2) production, is directly linked with obesity-driven metabolic derangements." (PMID 34099626, 2021). "In obesity, adipocytes produced several chemokines (Cxcl2, Cxcl12, Ccl2, etc.)recruiting macrophage and neutrophils, causing systemic inflammation, insulin resistance, and the dysfunction of local endothelial cells." (PMID 34722509, 2021). "Yet, gene expression of typical obesity-induced macrophage and cytokine genes Adgre (F4/80), Itgax (CD11c), Tnf, and Ccl2 remained unaltered by myeloid Acly deficiency in both eWAT and liver." (PMID 33981315, 2021). "As expected, obesity was associated to increased inflammation of the ileum, as revealed by the significantly higher mRNA expression level of Il1b, Ccl2 and, to a lesser extent, of Il6." (PMID 32244932, 2020). "When mice were fed a high fat diet, they showed signs of systemic inflammation (C5a, IL-6, CCL2, IL-1β), consistent with the notion that obesity is a risk factor to develop “a state of chronic low-level inflammation”." (PMID 32971872, 2020). "Obesity causes chronic, macrophage-driven inflammation within breast tissue, initiated by chemokine ligand 2 (CCL2) signaling from adipose stromal cells." (PMID 32731354, 2020). "Ob/ob mice, a commonly used mouse strain that spontaneously develops obesity due to leptin deficiency-induced hyperphasia, as well as diet-induced obese mice, display elevated levels of plasma Mcp-1 and Ccl2 adipose tissue expression." (PMID 32158768, 2020). "In this study, we demonstrated that HFD-induced obesity promoted the EAE severity by enhancing the CNS inflammation featured by pathogenic T cells activation in an CCL-2 and IL-6 dependent manner." (PMID 31507583, 2019).
Obesity (continued). "Obesity that is characterized by chronic low-grade systemic inflammation is associated with an elevated level of CCL2 and CCL5, which are the major chemokines involved in macrophage infiltration and the alteration of decoy receptor expression." (PMID 31817755, 2019). "It has been implicated that obesity can upregulate circulating CCL2 and TNF-α, the cause of obesity-associated insulin resistance and the development of type 2 diabetes." (PMID 31498850, 2019). "In obesity-associated breast cancer, adipocytes are able to recruit macrophages by a novel signaling pathway involving IL-1β and the chemotactic factor CCL2 (also known as MCP-1) that in turn activate CXCL12 promoting angiogenesis and tumor development." (PMID 30619282, 2018). "We measured mRNA levels of genes encoding for several markers of inflammation related to obesity, including the chemokine MCP1 (Ccl2), proinflammatory cytokine IL6 (Il6) and TNFα (Tnf), and macrophage-specific marker F4/80 (Emr1) in adipose depots." (PMID 25745505, 2015). "In other experimental models characterized by abnormal inflammatory skewing of MPs such as diabetes and obesity, CCL2 or CCR2 deficiency has also been linked to a switch away from excessive proinflammatory MP polarization." (PMID 25312642, 2014). "Recent data have conclusively shown a causal relationship between obesity-induced overproduction of fat inflammatory mediators such as Ccl2, insulin resistance and steatogenesis." (PMID 19513120, 2009). "In keeping, genetic or pharmacological inactivation of CB2 receptors decreased adipose tissue macrophage infiltration associated with obesity, and reduced inductions of Tnf and Ccl2 expressions." (PMID 19513120, 2009). "Together, these findings suggest that irisin may serve as an associative biomarker for identifying individuals at risk of obesity-related metabolic disturbances, whereas CCL2 and IL-1β may be more indicative of chronic adipose tissue inflammation." (PMID 42196825, 2026). "Consequently, blocking CCL2 with a nAb‐CCL2 more effectively limits the supply of FAs to tumors in an obese state, thereby exerting a stronger tumor‐suppressive effect in obesity‐associated breast cancer." (PMID 41160815, 2026). "Therefore, further studies should focus on studying how obesity-associated CC as well as IL-1β and CCL2 affect the macrophage differentiation directly in the TME." (PMID 39305371, 2025). "Additionally, weight loss causes a 20% decrease in circulating CCL2, which suggests that this chemokine plays a role in obesity-related complications." (PMID 39457105, 2024). "In the development of obesity pathology, weight loss has been shown to effectively lower CCL2 levels, thereby alleviating inflammation and reducing the risk of related conditions, such as macrophage activation, hepatocellular carcinoma, rheumatoid arthritis, and multiple myeloma." (PMID 39334887, 2024). "CCL2, as a key immunomodulatory molecule, promotes the migration of immune cells to adipose tissue and has a significant impact on the inflammatory process associated with obesity." (PMID 39334887, 2024). "However, another study has reported opposite results, suggesting that Caspase-1-deficient mice were more susceptible to high-fat diet-induced obesity and increased inflammation, primarily through the CCL2/C-C chemokine receptor 2 (CCR2) axis in adipose tissue." (PMID 38672517, 2024). "In a second reduced model, we eliminated all factors that did not fit the predictive model, in which, in addition to the CXCL10/CCL2 ratio (adjusted OR 15.9, p < 0.001), only the risk factors multiple gestation (adjusted OR 8.4, p = 0.006) and obesity remained (adjusted OR 6.6, p = 0.016)." (PMID 37770883, 2023). "In fact, obesity causes dramatic upregulation of CCL2, CCL7 and CCL8 in the AT." (PMID 36994095, 2023).
Obesity (continued). "However, in adipose tissue analyzed pre- and posttreatment, several adipose tissue cytokines and chemokines associated with obesity, including IL-6, MCP-1, C–C motif chemokine ligand 2 (CCL2), interleukin 7R and CX3CL1, were markedly less expressed." (PMID 35216214, 2022). "A cross-sectional study suggests that CCL2 may be a diagnostic biomarker for assessing inflammation and physical fitness in children with obesity." (PMID 34334083, 2021). "Excessive CCL2 expression associated with obesity may also contribute to the development of inflammation in the renal tubulointerstitial tissue." (PMID 34768469, 2021). "Consequently, we specifically chose to measure the levels of CCL2 to investigate its putative role as a diagnostic biomarker linking inflammation/obesity to CRC." (PMID 34639088, 2021). "Adipose tissue macrophages stimulated by free fatty acids, produce CCL2 that promote the recruitment of proinflammatory monocytes to the inflamed tissue, but L-10 may protect adipocytes from obesity, causing insulin resistance." (PMID 35010945, 2021). "Obesity-associated adipose inflammation, for instance, is characterized by increased infiltration of macrophages and other immune cells, and macrophage infiltration has been shown to be stimulated by obese adipose tissue expression of Ccl2/MCP-1." (PMID 35822007, 2021). "MiR-193b is expressed in high amounts in adipose tissue, where it contributes to the differentiation of brown adipocytes and to the decrease of inflammation through its inhibitory action on CCL-2 (chemokine C-C motif ligand 2), a key factor involved in inflammation associated with obesity." (PMID 34199293, 2021). "Moreover, in vitro experiments identified ten miRNAs dysregulated during obesity which are strongly associated with the secretion of CCL2." (PMID 33540898, 2021). "Furthermore, increases in expression of the SERPINE1 and ID3 genes, which are associated with obesity, and a decrease in pro-inflammatory CCL2 gene expression highlighted the impact of mechanical stretch on the cholesterol biosynthesis pathway." (PMID 32759460, 2020). "Our finding reveals a critical role of CCL-2 and IL-6 in obesity-associated CNS inflammation and that may be potential therapeutic targets for prevention and treatment of obesity-related MS." (PMID 31507583, 2019). "Our findings lead us to speculate that targeting IL-6 and CCL-2 is a possible therapeutic strategy for inhibition of obesity-associated CNS inflammation." (PMID 31507583, 2019). "The increase in ATM abundance during obesity is crucial for exacerbating the inflammatory response and is mainly caused by the recruitment of circulating bone marrow-derived monocytes through an MCP-1 (CCL2)/CCR2- dependent mechanism." (PMID 31277269, 2019). "Besides, the rs12075 G allele has also been related with low CCL2 levels in patients with chronic inflammatory diseases such as ischemia of the lower extremities and obesity, as well as low leukocyte counts in African people." (PMID 30970632, 2019). "Therefore, obesity can cause chronic inflammation with enhanced proinflammatory cytokines IL-6 and CCL-2 production, which have the immune-enhancing effect to boost the effector Th1 and Th17 cell responses in HFD EAE." (PMID 31507583, 2019). "In addition, CCL2 is widely recognized to be a major component of chronic inflammation associated with a variety of diseases including obesity-associated type 2 diabetes and cardiovascular diseases." (PMID 26355725, 2015). "A deficiency of MCP-1 (CCL2) or CCR2 (CCL2 receptor) in mice during obesity results in the impairment of CAMφ recruitment to adipose tissue, thus impeding the induction of insulin resistance by a high-fat diet (HFD) and suggesting an important role for CAMφs in T2D initiation and development." (PMID 23326021, 2012).